FGFR1 (fibroblast growth factor receptor 1)
Diseases named in the same sentence as FGFR1 in open-access papers (continued):
Sharing a sentence is not in itself a finding about the gene and the disease.
cancer (continued). "Our study supports the idea that FGFs/FGFRs are crucial for the survival of many cancer cells, and that targeting FGFR1 is a rational and effective strategy for therapy." (PMID 26201468, 2015). "In contrast, IMB-R1 recognizes both isoforms, so offering inhibition of FGFR1 signaling in cancers of either epithelial or mesenchymal origin." (PMID 26201468, 2015). "Immunostaining with IMB-R1 was stronger in human cancer tissues in which the FGFR1 gene is amplified." (PMID 26201468, 2015). "FGFR1 was another upregulated gene acting in pathways of cancer and also playing a role in the actin cytoskeleton signaling." (PMID 26998479, 2015). "Here, we identified ferulic acid as a novel fibroblast growth factor receptor 1 (FGFR1) inhibitor and a novel agent with potential anti-angiogenic and anti-cancer activities." (PMID 26473837, 2015). "Overall, FGFR1 amplification was homogenous in 20 (86.9%) and heterogeneous in 3 (13.0%) amplified cancers." (PMID 26555375, 2015). "In the development of cancer, FGFR1 is required for the proliferation of variety of cancer cell in which FGFR1 is amplified." (PMID 24980830, 2014). "FGFR inhibition resulted in cytoplasmic localisation of FGFR1 and FGF2, in contrast to vehicle-treated conditions where PSCs with nuclear FGFR1 and FGF2 led cancer cells to invade the underlying extra-cellular matrix." (PMID 24503018, 2014). "Meta-analysis of FGFR gene amplification status and OS in a variety of cancers was performed; 1345 patients in 6 studies for FGFR1 amplification and 1344 patients in 3 studies for FGFR2 amplification were included." (PMID 25171497, 2014). "There was also nuclear and cytoplasmic staining of FGFR1 in approximately 39% of cancer cells and approximately 37% of myo-fibroblasts." (PMID 24503018, 2014). "FGFR1 activation leads to the phosphorylation of ERK and Akt which are considered to be downstream signaling pathway of FGFR1, plays important role in the important roles in the proliferation and survival of cancer cells." (PMID 24980830, 2014). "Another possibility to explain the prevalence of centrosome protein fusion partners in MPN is that localization of the active FGFR1 kinase to the centrosome interferes with centrosome function in a manner beneficial to the cancer cell." (PMID 24658090, 2014). "Elevated levels of validated miR-133b targets such as CXCR4, FGFR1, FSCN1 has been associated with prognosis of various cancers." (PMID 24967583, 2014). "In contrast to the cytoplasmic localisation in well-differentiated cancer cell lines, FGFR1 was mainly nuclear in stellate cells (speckled distribution) and some poorly-differentiated cancer cell lines." (PMID 24503018, 2014). "FGFR1 localised to the nucleus in the stellate cells invading into the matrix, whereas those stellate cells remaining juxtaposed to cancer cells showed less frequent nuclear localisation." (PMID 24503018, 2014). "Among the numerous possible candidates, we picked out the ones overexpressed in cancers and proliferation- and metastasis-associated genes, including NOTCH2, FGFR1, CSF1, AGAP2, CREB1, for further analysis." (PMID 24614175, 2014). "In order to assess the relationship between nuclear FGF2 and FGFR1 in stellate and cancer cells, PS1, MIA PaCa-2 and COLO-357 cell lines were subjected to RNAi mediated knock-down of FGF2." (PMID 24503018, 2014). "Reduction of FGFR1-targeting miRNAs for cancer therapy deteriorate diabetes and cardiac functions, because the FGFR1-PI3K-AKT signaling cascade is involved in cancer promotion as well as diabetes control." (PMID 25364765, 2014). "Following FGFR blockade, PSCs remaining in the cancer cell layer displayed mainly cytoplasmic staining for both FGFR1 and FGF2." (PMID 24503018, 2014). "Whilst FGFR1 expression was weak in normal epithelial cell lines, it was stronger in many of the poorly differentiated cancer cells lines." (PMID 24503018, 2014).
cancer (continued). "FGFR1-mediated signaling is involved in cancer cell growth and infiltration, as well as in angiogenesis, which is already a target for antitumor therapies." (PMID 21573021, 2011). "Amplification of the membrane receptor genes EGFR and FGFR1 has been reported in various cancers including ESCC, and this phenomenon has been suggested to be a poor prognostic factor in solid tumors." (PMID 20163722, 2010). "Among the 86 tumors, pT3 carcinoma samples expressed FGFR1 and WT1 proteins more frequently than pT2 samples." (PMID 17137506, 2006). "FGFR1 levels in cancers tended to be higher in those which were oestrogen receptor positive (P less than 0.06)." (PMID 1380281, 1992). "Additionally, it has been documented that the phosphorylation of LDHA is regulated by FGFR1, a membrane receptor tyrosine kinase frequently overexpressed in various cancers." (PMID 41531896, 2026). "Considering the frequency of an FGFR1/FGF overstimulation in many cancers, the hyper-inhibitory effect of this Spry4 version on FGFR1-expressing cells is a valuable insight that can be used for the development of therapeutic concepts, especially to combat cancers with this overexpression." (PMID 40806483, 2025). "Furthermore, FGFR1 TKD mutations can cause conformational changes that enhance downstream signaling and further promote cancer cell survival." (PMID 40076427, 2025). "In conclusion, the presented results suggest that 5,7-dimethyl-oxazolo[5,4-d]pyrimidine-5,7(4H,6H)-dione derivatives may serve as potential agents for the treatment of FGFR1-mediated cancers." (PMID 39942770, 2025). "As a result, the possibility exists that elevated levels of ATP could contribute to increased kinase activity of FGFR1 in cancer cells." (PMID 40643473, 2025). "Therefore, understanding the structural basis of FGFR1–heparin interactions not only advances our knowledge of receptor biology but also opens avenues for targeted cancer therapies." (PMID 41226200, 2025). "The FGFR1–heparin interaction is fundamental to effective FGF-mediated signal transduction and is implicated in numerous physiological and pathological processes, including cell proliferation, differentiation, angiogenesis, and cancer progression." (PMID 41226200, 2025). "In addition, FGFR1 overexpression enhances cancer cell stemness and activates Akt/Erk–ER signaling, promoting palbociclib resistance in luminal A BC cells." (PMID 41049266, 2025). "However, in cancer, dysregulation of FGFR1 signaling, often due to gene amplification or overexpression, leads to uncontrolled cell proliferation and tumorigenesis." (PMID 40547805, 2025). "Targeted therapies designed to inhibit specific pathways, such as the PI3K/AKT/mTOR pathway or FGFR1 signaling, may be considered for cancer patients exhibiting these genetic aberrations." (PMID 38674331, 2024). "Alterations in FGFR1 can lead to constitutive activation of signaling pathways that drive oncogenesis by promoting uncontrolled cell division, inhibiting apoptosis, and enhancing the metastatic potential of cancer cells." (PMID 39590377, 2024). "Similarly, the NCI-MATCH trial revealed restricted effectiveness of AZD4547 in refractory cancers exhibiting FGFR1-3 aberrations, with responses observed solely in tumors harboring FGFR1-3 point mutations or fusions." (PMID 38831455, 2024). "Future efforts that consider combination therapeutic strategies may overcome the limitations of single-agent FGFR inhibition in FGFR1 amplified cancers, might serve as a potential clinical approach for enhancing efficacy and minimizing unexpected outcomes." (PMID 38553760, 2024). "This suggests that FGF2 and FGFR1 amplification promoted cancer stemness." (PMID 38553760, 2024). "Furthermore, we have compiled a comprehensive overview of current therapies targeting FGFR1 aberration in cancer, aiming to offer new perspectives for future cancer treatments by focusing on drugs that address specific FGFR1 alterations." (PMID 39590377, 2024).
cancer (continued). "Regulation of PD-L1 expression in K-ras-driven cancers through ROS-mediated FGFR1 signaling." (PMID 37469162, 2024). "In the next step, we investigated whether honokiol could attenuate or nullify the protective effects of FGF1 on FGFR1-expressing cancer cells treated with the drug targeting tubulin polymerization, taltobulin." (PMID 39329123, 2024). "Additionally, the expression of FGFR1 D647N significantly enhances both individual and collective migration of cancer cells in vitro and in vivo, activating and mediating the PI3K/AKT signaling pathway." (PMID 39590377, 2024). "Our study aimed to verify whether blocking FGF1/FGFR1 activity with honokiol or an FGF ligand trap is able to re-sensitize cancer cells to taltobulin and prevent the development of long-term drug resistance." (PMID 39329123, 2024). "Nucleus FGFR1 could interact with chromatin and regulate gene transcription to promote cancer progression." (PMID 37490511, 2023). "The discovery of recurrent FGFR1 amplifications (located on 8p11.23) had raised hopes that patients with such amplification might benefit from FGFR inhibition in this hard-to-treat cancer." (PMID 37606995, 2023). "However, similar to the pattern of amplification observed in patient samples and cancer cell lines, FGFR inhibitor–sensitive PDX specimens had FGFR1/NSD3-centered amplification, whereas FGFR-deficient samples showed no clear center of amplification." (PMID 37606995, 2023). "Distinct rearrangements within the 8p11-p12 locus associate with sensitivity to FGFR inhibition in cancer models lacking ectodomain-deficient FGFR1." (PMID 37606995, 2023). "Fibroblast growth factor receptor 1 (FGFR1) can promote cancer progression." (PMID 37415736, 2023). "If there was a clinical trial indication at level C or D for a specific cancer type, such as amplification of MDM2 or FGFR1 or mutations of AKT1, ATM, CDK12, and PTEN, patients were considered as candidates for receiving treatment, although in most cases, no clinical trials were available." (PMID 36251535, 2023). "Complementary insights into the possible mechanism of their anti-cancer activity were provided by molecular docking calculations, exploring their ability to bind to the overexpressed fibroblast growth factor receptor 1 (FGFR1), affecting cancer cells’ functionalities." (PMID 36615533, 2023). "Finally, molecular docking calculations shed light on the in vitro anti-cancer activity of the compounds, suggesting a possible role on the FGFR1 target protein, affecting cancer cells’ functionalities." (PMID 36615533, 2023). "The diversified mode of action of the dual-warhead conjugate may help to overcome the potential acquired resistance of FGFR1-overproducing cancer cells to single cytotoxic drugs." (PMID 37373291, 2023). "Nuclear FGFR1 has been shown to interact with the CBP/CREB complex, Nurr1, RNA polymerase II or FOXA1 and has so far been mainly associated with the regulation of gene expression in healthy and cancer cells." (PMID 37480072, 2023). "Besides metastasis, LIN28 and FGFR1 are closely correlated with cancer cell growth and drug resistance." (PMID 34913237, 2022). "FGFR1 expression has been reported in multiple cancer types including HCC." (PMID 35683481, 2022). "The overexpression of FGFR1 has been reported to promote NF-kappaB signaling in cancer." (PMID 35081975, 2022). "AZD4547 is an oral TKI selective for FGFR1, 2, and 3 which showed only a modest activity in patients with advanced cancer who harbor FGFR1, 2, or 3 alterations and enrolled in the arm of the National Cancer Institute—Molecular Analysis for Therapy Choice (NCT02465060)." (PMID 35875139, 2022). "8p11, creates a synthetic dependency on FGFR1 signaling in cancer." (PMID 35626002, 2022). "Since FGFR1–4 mutant cancers have an unfavorable prognosis, the combination of radiotherapy with FGFR inhibitors may be a viable treatment option for this subset of cancers." (PMID 35681425, 2022).
cancer (continued). "Several FGFR1 inhibitors were developed for cancer treatment." (PMID 36676646, 2022). "FGFR1 loss and TOP2A loss are promising new biomarkers that independently identify a subgroup of triple negative poor prognosis PABC patients that require personalized cancer treatment." (PMID 35792986, 2022). "We further investigated whether FGF1 stimulation could suppress drug-induced apoptosis in cancer cells expressing FGFR1." (PMID 36276073, 2022). "Fibroblast growth factor receptor 1 is involved in the regulation of FAK phosphorylation and MMP‐9 expression via the FGFR‐extracellular regulated kinase‐FAK pathway, which has been implicated in the invasion, metastasis, and motility of cancer cells." (PMID 34913237, 2022). "There have been many reports about the close relationship between FGFR1 and cancer development." (PMID 36230646, 2022). "Our findings may contribute to the development of more effective therapies and may facilitate the prevention of drug resistance in FGFR1-positive cancer cells." (PMID 36276073, 2022). "This suggests that both canonical (PI3K-dependent) and alternative (PI3K-independent) AKT-activating pathways may regulate FGF1/FGFR1-driven cancer cell survival." (PMID 36276073, 2022). "Given the independent roles of FGFR1 and galectins in cancer, we suggest that galectins could be of relevance when considering targeted therapies regulation of FGFR1 signaling." (PMID 34068954, 2021). "While the interplay between L1CAM and FGFR1 signaling has been extensively documented in the nervous system where it enhances neurite outgrowth, little information is available on its possible involvement in cancer cells." (PMID 34645505, 2021). "We sought to construct a platformfor the efficient generationof self-assembling, high-affinity, efficiently internalizing, oligomericFGFR1-targeting molecules that could serve as drug delivery agentsfor the precise treatment of FGFR1-dependent cancers." (PMID 34855396, 2021). "As a molecular target we selected FGFR1, a receptor overproduced by numerous cancer types." (PMID 34635096, 2021). "Interestingly, the mRNA levels of FGFR1 and FGFR3 in EPN tissues across all EPN subtypes were at least as high as the levels in the well-described FGFR-driven cancer cell models NCI-H1703 (FGFR1, NSCLC) and Hep3B (FGFR3, HCC) (respectively)." (PMID 34046693, 2021). "Importantly, we have positively evaluated T-Fc as an effective drug delivery vehicle as the T-Fc-vcMMAE displayed potent and selective cytotoxicity against FGFR1-positive cancer cells." (PMID 33962559, 2021). "Cancers with FGFR1 amplification have shown low response rates to AZD4547." (PMID 34639155, 2021). "FGFR1 amplification and/or overexpression is frequently detected in breast and other cancers." (PMID 34831231, 2021). "Whether differential expression of FGFR1/2/3 or the effector FRS2 correlated with sensitivity of cancer cells to FGFR inhibitors remains to be investigated." (PMID 34369083, 2021). "In addtion, FGFR1 has been reported to regulate the biologocal processess, including wound repair, tissue regeneration, inflammation and angiogenesis, which are implcated in cancer progression and drug resistance." (PMID 34899853, 2021). "FGFR1 can be considered a therapeutic target for many cancers from different tissues." (PMID 34114373, 2021). "Since the T-Fc employs multiple endocytic pathways, T-Fc-FGFR1 complexes are less prone to alterations in protein trafficking in cancer cells, suggesting that the T-Fc could constitute highly attractive drug carrier for ADC approach." (PMID 33962559, 2021).
cancer (continued). "GZD824 strongly suppresses FGFR1–3 and effectively overcomes FGFR1‐V561F/M and other mutant resistance in vitro and in vivo, and may serve as a novel drug in clinical trials of cancer therapy." (PMID 34114373, 2021). "Based on the largely improved affinity for FGFR1 and the simplicity of preparation we selected the tetrameric variant of FGF1-SA as a basis for development of selective cytotoxic conjugates targeting cancer cells overproducing FGFR1." (PMID 34635096, 2021). "Interestingly, inhibition of the mTOR pathway, but not the PI3K pathway, in triple-negative breast cancer cells led to increased FGF1 and Notch1 expression, enhanced FGFR1 activation and the formation of a resistant cancer stem cell-like population." (PMID 34830951, 2021). "Finally, research into the value of FGFR1 in cancer diagnosis should be performed in order to assess its usefulness for potential clinical application." (PMID 33604191, 2021). "Moreover, tyrosine 10 (Y10) phosphorylation of LDHA, which is rampant in diverse cancers, is also correlated with several oncogenic tyrosine kinases, including fibroblast growth factor receptor 1 (FGFR1)." (PMID 34452627, 2021). "However, the FGFR1 8p11/12 amplicon is often broad, with FGFR1 signaling likely a driver only in a subset of cancers." (PMID 32940689, 2021). "Low molecular weight chemical inhibitors, ligand traps, antibodies and their fragments, and a few cytotoxic conjugates have been developed to either block abnormal FGFR1-dependent signaling that facilitates cancer cell proliferation and survival, or to selectively kill FGFR1-overproducing cells." (PMID 34635096, 2021). "FGFR1 is a tyrosine kinase receptor which enhances cancer cell migration." (PMID 33637089, 2021). "Detection of FGFR1 in mitochondria has been reported previously for cancer cell lines." (PMID 34685716, 2021). "Furthermore, FLT1 of LUSC, ITGB1 of DLBC, MDM4, and CDKN1A of ACC, MAPK1, and ERBB3 of UCEC, FGFR1 of ESCA, and EREG and BCL2L1 of COAD have been strongly associated with patient survival in their respective cancers." (PMID 34079798, 2021). "In conclusion, CERS6-AS1 promoted the oncogenicity of PDAC by serving as a competing endogenous RNA to sequester miR-15a-5p and increase FGFR1 expression, which highlights the potential of the CERS6-AS1/miR-15a-5p/FGFR1 pathway as an effective target for cancer therapy." (PMID 33581689, 2021). "Since then, strategies are underway to regulate FGFR1-modulated cancer initiation and progression." (PMID 34722544, 2021). "In particular, the FGFR1 gene (located on chromosome 8p11-12) is mutated in many cancers, while the other receptors are not frequently mutated." (PMID 33535617, 2021). "FGFR2 amplifications are the second most common amplifications of FGFR1-4 in cancer." (PMID 34068954, 2021). "The highly effective and selective internalization of T-Fc suggested that this engineered antibody may constitute an ideal drug delivery vehicle for FGFR1-overproducing cancer cells." (PMID 33962559, 2021). "The exact mechanism underlying the association of FGFR1 with cancer incidence has not been clearly elucidated." (PMID 33989301, 2021). "PeptibodyF2 was internalized into FGFR1 overexpressing cells strictly via receptor-mediated endocytosis, suggesting that it may serve as a drug carrier for selective elimination of FGFR1-bearing cancer cells." (PMID 33076489, 2020). "Both FGFR1 and Src play a key role in cancer progression and it is therefore anticipated that the development of these novel anticancer agents could have a broad spectrum of application in different cancer settings." (PMID 33287862, 2020). "In addition, activation of FGFR1 promotes the development of epithelial-mesenchymal transition (EMT) in several human cancers." (PMID 32202509, 2020). "In addition, we examined significant relationships between the mRNA co-expression of FGFR1 and LepR in 29 primary cancers." (PMID 33019728, 2020).